EGFR (epidermal growth factor receptor)
Diseases named in the same sentence as EGFR in open-access papers (continued):
Sharing a sentence is not in itself a finding about the gene and the disease.
tumor (continued). "We hypothesized that anti-EGFR therapy might increase the number of genomic alts in the tumor." (PMID 30705875, 2018). "In addition, one EGFR-mutated tumor exhibited MET-overexpression without MET-amplification, suggesting other mechanisms increasing the receptor expression in this case." (PMID 29899852, 2018). "In addition, blockage of the EGFR enhances skin inflammation by inducing chemokine expression." (PMID 30093649, 2018). "In addition to its putative value as non-invasive diagnostic tool, we hypothesised that plasma beta-arrestin-1 measurement might aid in the prediction of tumour response to EGFR inhibitor therapy." (PMID 30078843, 2018). "We aimed to analyze whether EGFR expression in DFSP and DFSP-T was associated with EGFR activation through phosphorylation, and to determine which downstream signaling pathways were preferentially activated in DFSP tumor progression." (PMID 29492209, 2018). "Similarly to our in vitro data with ZEGFR:03115–IR700DX, in vivo imaging studies demonstrated that the conjugate penetrates deeply in the EGFR highly expressing U87‐MGvIII subcutaneous and orthotopic tumors, allowing for clear tumor visualization as early as 1 h post‐injection." (PMID 29313975, 2018). "Thus, the result showed that there was no relation between the decrease of EGFR mutation abundance and tumor response." (PMID 30400855, 2018). "By contrast, patients with tumours that are wild-type for EGFR have better outcomes with conventional platinum-based chemotherapy than EGFR TKIs and lack of an activating EGFR mutation could be considered a contraindication to EGFR TKI therapy." (PMID 29914100, 2018). "Among the 23 EGFR-mutated patients treated with erlotinib, 17 (74%) responded, 4 (17%) had no OR, and 2 (9%) harboring a SMAD4-mutation (p.R135*(stop)) and a FGFR3-mutation (p.D785fs*31), respectively, showed mixed response with simultaneously progressing and responding tumor lesions." (PMID 29899852, 2018). "Direct suppression of BRD4-NUT and concurrent downregulation of other tumor promoting genes such as EGFR and CDK2 by miR-3140 may potentially overcome resistance to BET inhibitors in NMC cells, although further studies are needed to clarify the acquired resistance of BET inhibitiors." (PMID 29540837, 2018). "Interestingly, none of EGFR TKD mutated patients had a tumor response, even if the correlation is not statistically significant (p = 0.07, data not shown)." (PMID 29352306, 2018). "Consequently, preclinical development of novel effective EGFR-inhibitors would require a reliable holistic human assay platform generating both target-mediated efficacy and safety data based on the homeostasis of a patient’s skin and tumour tissue co-culture." (PMID 30301942, 2018). "This argues for mutation-specific (as opposed to tumor-type specific) responses to EGFR-TKIs." (PMID 30518123, 2018). "Therefore, we sought to determine whether EGFR amplification correlated with heterogeneity in individual tumor cell migration patterns." (PMID 30573757, 2018). "However, activating EGFR mutations can result in constitutive activation of the receptor, independent of ligand binding, leading to tumor development and growth." (PMID 29914100, 2018). "Thus, downregulation of CDK2 and EGFR may partially contribute to miR-3140-mediated suppression of tumor cell growth." (PMID 29540837, 2018). "This may explain, how As2O3 suppresses EGFR-expressing tumor cells." (PMID 29535630, 2018). "Main tumor resection was still a valuable procedure for patients who were negative or unknown for EGFR mutation." (PMID 29435191, 2018).
tumor (continued). "On the other hand, we believe that in patients with negative or unknown EGFR mutation status, main tumor resection is beneficial and recommended if feasible." (PMID 29435191, 2018). "The epidermal growth factor receptor (EGFR) family activates signaling pathways regulating cellular proliferation, angiogenesis initiation, apoptosis inhibition and survival, which subsequently results in increasing tumor masses and chemotherapy refractoriness." (PMID 29867487, 2018). "The most frequently mutated genes across all tumor types included KRAS (30 patients), PIK3CA (16 patients), BRAF (6 patients), EGFR (5 patients), NRAS (4 patients) and ERBB2 (3 patients) whereas CCND1, ERBB2, EGFR and MYC were the genes most frequently subjected to copy number gain." (PMID 29854313, 2018). "Thus, the detectability of the cobas EGFR test may be increased by enriching for tumor tissue, e.g., by macrodissection, but this manipulation requires extra time and effort." (PMID 29323170, 2018). "The high tumor mutational burden, typical phenotype of MSI-high tumors, could activate multiple oncogenic signals and thus negatively interfere with the therapeutic inhibition of a single pathway, i.e., EGFR blockade." (PMID 30081606, 2018). "Furthermore, EGFR levels were also significantly higher in the lung tissues (both tumor (T) and non-tumor (NT)) of MGL-deficient mice (lanes 2–5 and 7–10) compared to those in the MGL wild-type animals (lanes 1 and 6)." (PMID 29348400, 2018). "Additionally, they found that 7A7 could inhibit EGF-induced EGFR signaling in D122 tumour cells, triggering tumour regression in a T-cell dependent manner." (PMID 29552307, 2018). "To conclude, our results showed that both NDRG1 overexpression and treatment with DpdtC caused significant inhibitory effect on HER2/EGFR heterodimer formation and ERK1/2 activation, which may be a novel mechanism involved in the potent anti-tumor activity of DpdtC." (PMID 29467385, 2018). "Longitudinal analysis of tumour‐derived cell‐free DNA levels tracks tumour responses and reveals heterogeneous resistance mechanisms: The majority depend on the EGFR pathway while a small subset developed alterative drivers that could be identified by tracking multiple mutations in plasma DNA." (PMID 29848757, 2018). "Furthermore, this inhibition might slow the development of acquired resistance in patients with initially EGFR-dependent tumours, therefore providing greater clinical benefit than EGFR inhibition alone." (PMID 29254887, 2018). "The 1D8N/CEGa1 trimerbody may be able to maximize tumor-specific costimulation due to the combination of a higher total tumor uptake and substantially faster circulatory clearance, ultimately giving an improved T/N ratio as compared to conventional IgG-based anti-EGFR and anti-4-1BB antibodies." (PMID 30442944, 2018). "Thus, although perinuclear accumulation of EGFR can bring about short-term protection, in practice, it may be that perinuclear accumulation of EGFR in cells in a tumor indicates a state of prolonged p38 activation that precedes cell death." (PMID 28646091, 2017). "Interestingly, studies have shown that BC patients have lower serum EGFR (sEGFR) levels than age-matched healthy controls, while in other tumor entities, such as glioblastoma and head and neck squamous cell carcinoma, sEGFR levels in patient samples were significantly higher than in controls." (PMID 29229933, 2017). "Therefore, we proposed the hypothesis that the EGFR-mediated downstream pathway in the initiation of CSCs may be a target for discovering potent tumor therapeutic agents against cancer stemness." (PMID 28787001, 2017). "This suggests that RHOB expression levels determine the efficacy of EGFR signaling and led us to hypothesize that RHOB levels could account for the initial sensitivity of tumor cells to EGFR‐TKI through a mechanism that may involve EGFR‐dependent AKT signaling." (PMID 28003335, 2017).
tumor (continued). "Therefore, it can be hypothesized that a small pool of high-affinity EGFRs are ligand-occupied in tumor xenografts and sufficient to drive EGFR-dependent tumorigenesis." (PMID 29268862, 2017). "Other contributing factors could be the use of very low cut-off value of EGFR positivity in the earlier studies (i.e. EGFR positivity when immunostaining is present in ≥1% of tumour cells), and discordance between the expression of EGFR in the primary tumour and the metastatic sites." (PMID 28032593, 2017). "However, this suggestion was substantially based around the fact that many tumors strongly overexpress the EGFR, and it was assumed that such an extreme overexpression of this receptor would supposedly lead to higher sensitivity of the tumor cells to growth factor-induced proliferation." (PMID 28970798, 2017). "Thus, PET/CT imaging with 18F-IRS could potentially become a new approach for diagnosing NSCLC molecular-genetic patient subtypes as well as other EGFR-driven tumor types." (PMID 28600491, 2017). "Interestingly, this inhibition only occurred in cetuximab-sensitive but not in cetuximab-resistant HNSCC cell lines, data that argues in favor of a metabolic immunoescape mechanism to EGFR inhibition of HNSCC cells mediated by lactate acidification of the tumor milieu." (PMID 28611673, 2017). "However, EGFR gene-deletion in macrophages did influence tumor development." (PMID 28970798, 2017). "Ultimately, our understanding of EGFR-mediated escape mechanisms has led us to design EGFR-specific monoclonal antibody therapies that not only inhibit tumor cell metabolic changes and intrinsic oncogenic signaling but also activates immune cells that mediate tumor clearance." (PMID 28611673, 2017). "In the treatment of NSCLC cases that harbor epidermal growth factor receptor (EGFR) mutations, EGFR-tyrosine kinase inhibitors (TKIs), such as gefitinib, erlotinib, and afatinib, can block the survival signals that are mediated by this driver oncogene and can induce marked tumor regression." (PMID 28619066, 2017). "Since the EGFR mutation subtype (G719S) was not covered by the current ADx-SuperARMS EGFR assay, this case with G719X mutation was defined as a wild type in both plasma and tumor tissue in the following comparisons and therefore the total inconsistent cases between the paired samples were eleven." (PMID 28829813, 2017). "Finally, we generated a virtual patient population using published clinical data on BRAF, MEK, and EGFR antagonists, which accurately predicted population level-tumor responses to single agent treatment with the ERKi GDC-0994, and projected strategies to increase the single agent responses." (PMID 28649441, 2017). "After treatment the tumour partial oxygen pressure was measured by LiPc electron paramagnetic resonance oximetry and the expression of epidermal growth factor receptor (EGFR), phosphorylated EGFR, Ki-67, MCT1, MCT4, GLUT1, CAIX and HIF-1α were investigated by immunohistochemistry." (PMID 28756482, 2017). "The presence of EGFR sensitizing mutations may improve tumour response rate but not survival in patients with localized NSCLC treated with definitive thoracic radiation therapy with or without chemotherapy." (PMID 29312641, 2017). "Beside p.T790MEGFR and MUTKRAS, other mechanisms of acquired resistance not evaluated in our study have been described in tumor re-biopsies after EGFR-TKI progression, including actionable mutations of MET, HER2, PIK3CA or transformation into small cell histology (3%)." (PMID 26799287, 2017). "Furthermore, EGFR levels decreased in the shREP1 tumor compared with the shEV tumor." (PMID 28230863, 2017). "Thus, a high tumor EGFR expression may potentially be predictive of survival benefit from cetuximab based therapy for advanced NSCLC cases." (PMID 29246028, 2017).
tumor (continued). "In addition to the RET, the superexpression of receptors 2 and 3 of the vascular endothelial growth factor (VEGF), which leads to tumor angiogenesis and nutrition, and of the epidermal growth factor receptor (EGFR), involved in tumor proliferation, also contributes to the pathogenesis of MTC." (PMID 28658345, 2017). "However, the process of TKI-sensitive tumor re-progression and whether re-biopsy is possible in all cases of acquired resistance to EGFR-TKI remain unclear." (PMID 29212495, 2017). "MMP‐13 cleaves the Ln‐5 fragments Ln‐5γ2ʹ and Ln‐5γ2x into smaller fragments, which prevents the transfer of the EGFR molecular signal into the cell, preventing the signal from inducing the rearrangement of the actin cytoskeleton and affecting the vascular phenotype of aggressive tumour cells." (PMID 28766880, 2017). "Several studies had confirmed that EGFR mutations in NSCLC could be detected in ctDNA, and a meta-analysis reported that ctDNA offered 62.00% sensitivity and 95.90% specificity compared with tumor tissue DNA among the Asian population." (PMID 28978074, 2017). "The protease MMP-2 is not typically associated with tumor invasion but it is indicated that integrin-mediated EGFR signaling is activated through the direct binding of MMP-2 and PAK4 (a serine/threonine kinase that is involved in the regulation of cell motility, invasion, and growth)." (PMID 28629170, 2017). "Third, as patients who received anti-EGFR therapy were analyzed retrospectively, we could not definitively associate primary tumor sidedness with response to anti-EGFR therapy." (PMID 29212173, 2017). "Thus, it is reasonable to assume that EGFR antagonist interference with any of these leukocytes' function may advantageously contribute to the clinical efficacy of anti-tumor treatments." (PMID 28970798, 2017). "Notably, comparison of solid tumor and liquid biopsies from these patients revealed similar results in the ratios of wild type to mutant EGFR detected, indicating that liquid biopsies may be suitable for longitudinal assessment of a patient’s tumor." (PMID 28431544, 2017). "Therefore, EGFR blockade may not only diminish the tumor cell intrinsic EGFR-induced PD-L1 upregulation but also the cell extrinsic IFNγ-mediated signals that have been associated with CD8+ T cell infiltration in the TME." (PMID 28611673, 2017). "In SCCHN, the constitutive activation of STAT3 is responsible for tumour-immune evasion, producing immunosuppressive mediators and creating an immune tolerant microenvironment, In light of this, EGFR-independent STAT3 activation could contribute to a reduced response to cetuximab." (PMID 31093349, 2017). "Therefore, our findings demonstrated that CD73 may play a tumor-promoting role in NSCLC via its effects on EGFR signaling." (PMID 28158983, 2017). "Therefore, we aimed to identify a panel of circulating plasma microRNAs that can distinguish between NSCLC patients with EGFR-sensitive mutations and EGFR wild-type patients and to explore the potential of this microRNA panel to monitor tumor responses to EGFR-TKI treatment." (PMID 28496005, 2017). "Therefore, the canine EGFR, expressed by canine cancer cells, could be targeted by cetuximab which led to tumor growth inhibition, similarly to the effects observed on human cancer cells." (PMID 29137329, 2017). "Furthermore, activation of downstream signal transduction pathways (MEK/ERK) by EGFR has been shown to inhibit apoptosis in normal keratinocytes by increasing CyclinD1 and Bcl-2 levels, promoting formation of blood vessels and enhancing tumor survival." (PMID 28915593, 2017). "Moreover, via its constant domain, can225IgG could bind to Fcγ-receptors of canine immune cells and thereby mediate antibody-dependent cellular cytotoxicity (ADCC) and phagocytosis (ADCP) of EGFR+ tumor cells." (PMID 29137329, 2017). "Therefore, the development of novel tumor-targeting drugs for EGFR has become more and more urgent." (PMID 28181832, 2017).
tumor (continued). "Together, our data indicate that erlotinib therapy induced the evolution of multiple concurrent events that re-shaped the polyclonal tumor genetic landscape during the onset of resistance; resistance could be overcome by polytherapy against both EGFR and MAPK signaling in preclinical models." (PMID 28287179, 2017). "Therefore, a negative result of a captured tissue sample cannot represent the absence of EGFR mutations in the entire tumor." (PMID 29340107, 2017). "EGFR/HER2 inhibition may create a more favorable milieu for tumor immunotherapy." (PMID 28969039, 2017). "Additionally, it is also possible that PAD inhibitors may synergize with EGFR inhibitors to suppress tumor growth." (PMID 28549415, 2017). "Therefore, we hypothesized that EGFR gene copy number alteration in the primary tumor could predict amplification in recurrent tumors, lymph node metastatic foci or secondary primary tumors." (PMID 28854970, 2017). "However, tumor tissue samples are not always available for EGFR mutation detection in clinical practice." (PMID 28052016, 2017). "Furthermore, both of these mechanisms could lead to persistent activation of ERK signaling, thus circumventing the anti-tumor effects of anti-EGFR therapy." (PMID 28002810, 2017). "Radionuclide imaging of EGFR expression in tumours may aid in selection of optimal cancer therapy." (PMID 28729680, 2017). "Furthermore, genomic amplification of EGFR was variable in the PDX models over several in vivo passages as well as in comparison to the primary GBM in all cases with EGFR amplification in the primary tumor." (PMID 28183348, 2017). "Notably, molecular screening of CTCs and ctDNA identified the T790M EGFR mutation in 35% of patients (n=14) with negative or indeterminate tumor sample findings." (PMID 29312651, 2017). "As another example, ctDNA analysis in BR28 showed that EGFR p.R521K and PTCH1 p.T1195S variants were more frequent than ATM pH1380Y, BRCA2 p.N289H, and BRCA2 p.N991D, whereas all these variants were present at a similar frequency in tumor tissue samples at diagnosis and after the 1st NAC cycle." (PMID 29156805, 2017). "Indeed, specific miRNAs profiles are associated to EGFR, KRAS or WT tumours." (PMID 28771186, 2017). "Moreover, our center has established its own follow-up protocol since 2004, and tumor assessments for patients treated with EGFR-TKIs were strictly performed following the protocol at every 8 weeks in clinical practice (n = 60) and every 6 weeks in clinical trials (n = 6)." (PMID 27999211, 2017). "Moreover, in some frail patients, or if the tumor lesion is not accessible to a tissue biopsy, a liquid biopsy can also detect some activating mutations in EGFR on initial assessment." (PMID 28805673, 2017). "In addition to XIAP, EGFR is also a well-known tumor therapeutic target." (PMID 28057023, 2017). "Furthermore, in the case of EGFR-NSCLC where tumor tissue may be hard to obtain, genotyping for the BIM deletion may be performed on normal tissue, e.g from peripheral blood mononuclear cells or even a buccal swab." (PMID 29100409, 2017). "In addition to the challenge of implementing bio-markers for predicting response or resistance to anti-EGFR therapy, another challenge faced by the use of EGFR inhibitors is that the duration of the response is often limited and many tumours invariably develop resistance." (PMID 28513565, 2017). "For patients whose tumor tissue is not enough or unavailable, EGFR mutation detection with CastPCR in cfDNA could be first choice." (PMID 28572536, 2017). "A majority of studies applying morphological criteria have described their tissue as EGFR positive when staining occurs in the cell membrane, while others have included cytoplasmic staining or mixed cytoplasmic/membranous staining or have specifically evaluated staining in the tumor stroma." (PMID 28740577, 2017). "Overexpression of EGFR may confer or promote a malignant phenotype and increase the tumor mass." (PMID 29276515, 2017).